VWA8 (von Willebrand factor A domain containing 8)
Description:
Exhibits ATPase activity in vitro.
Synonyms: P7BP2; KIAA0564; RP97
Tractability: PROTAC: ubiquitination databases record sites on it; its protein half-life has been measured.
Gene: Protein-coding gene on chromosome 13 (41,566,834 to 41,961,129, reverse strand). Ensembl gene ENSG00000102763.
Subcellular location: Mitochondrion (Isoform 1); Mitochondrion (Isoform 2); Peroxisome
Subcellular location (Human Protein Atlas): Lipid droplets; Vesicles
Gene Ontology:
Molecular function: protein binding; ATP hydrolysis activity; ATP binding
Cellular component: mitochondrion; peroxisome; cytoplasm
Genetic constraint (gnomAD): Loss-of-function variants: 175 observed, 199.79 expected, observed/expected ratio (o/e) 0.88, 90% interval 0.77 to 0.99. The upper end of that interval is the gene's LOEUF score, 0.99, which puts it in group 4 of 6, group 1 being the genes least tolerant of losing a copy. Missense variants: 2,154 observed, 2,222.1 expected, observed/expected ratio (o/e) 0.97, 90% interval 0.94 to 1. Synonymous variants: 808 observed, 797.21 expected, observed/expected ratio (o/e) 1.01, 90% interval 0.96 to 1.07.
Homologues: Orthologues: chimpanzee VWA8 (99% identical), macaque VWA8 (98% identical), guinea pig VWA8 (90% identical), dog VWA8 (87% identical), rabbit VWA8 (87% identical), rat Vwa8 (87% identical), mouse Vwa8 (86% identical), pig VWA8 (86% identical), tropical clawed frog vwa8 (74% identical), zebrafish vwa8 (71% identical), Drosophila melanogaster c12.2 (38% identical), Caenorhabditis elegans vwa-8 (37% identical).
Diseases named in the same sentence as VWA8 in open-access papers:
VWA8 is named in the same sentence as 21 diseases in open-access papers, as found by Europe PMC text mining. Sharing a sentence is not in itself a finding about the gene and the disease. The quoted sentences say what the papers report.
autism (2 papers, 2021 to 2024). Persistent deficits in social interaction and communication and interaction as well as a markedly restricted repertoire of activity and interest as well as repetitive patterns of behavior. "VWA8 has been linked to neurological disorders such as autism and bipolar disorder in various genome-wide associated studies, while SNAP29 has been proposed as a candidate of genetically based psychiatric disorders such as schizophrenia and bipolar disorder in previous studies." (PMID 39727940, 2024). "The KO Vwa8 was also associated with variations in the corpus callosum size, responsible for multiple behavioral and cognitive disorders in humans, such as schizophrenia, autism, attention deficit hyperactivity, and bipolar disorder." (PMID 34660594, 2021).
bipolar disorder (2 papers, 2021 to 2024). A disorder of the brain that causes unusual shifts in mood, energy, activity levels and the ability to carry out day-to-day tasks. "Similarly, a study linked human Vwa8 SNPs comorbid migraine and bipolar disorder." (PMID 34660594, 2021). "VWA8 (von Willebrand domain-containing protein 8), SNAP29 (Synaptosomal-associated protein 29), RIF1 (Replication Timing Regulatory Factor 1), AQP4 (Aquaporin-4) and GSTM3 (Glutathione S-Transferase Mu 3) were some relevant differentially expressed genes detected in the bipolar disorder datasets." (PMID 39727940, 2024). "VWA8 and SNAP29 were significantly up-regulated in our analysis of the bipolar disorder datasets using the CASh method." (PMID 39727940, 2024).
breast carcinoma (2 papers, 2022 to 2023). "Upregulation of VWA8 expression was negatively correlated with brain metastasis associated with breast cancer (Yuan, Wang & Cheng, 2018)." (PMID 38054015, 2023). "von Willebrand factor A domain-containing 8 (VWA8) were found to be significantly downregulated in breast cancer brain metastases." (PMID 35053843, 2022).
microcephaly (2 papers, 2021 to 2023). A congenital or acquired developmental disorder in which the circumference of the head is smaller than normal for the person's age and sex. "This is the first homozygous variant identified in the VWA8 gene underlying global developmental delay, microcephaly, scoliosis, limbs, and cardiovascular malformations in humans." (PMID 34660594, 2021). "VWA8 depletion in human and zebrafish causes developmental deficits with microcephaly." (PMID 38139332, 2023). "Our zebrafish data strongly suggest the conserved function of vwa8 in humans and zebrafish supported by the observation of phenotypic hallmarks including developmental delay, microcephaly, and scoliosis in morpholino injected fish resulting in knockdown of vwa8." (PMID 34660594, 2021).
autism spectrum disorder (1 paper, 2021). A spectrum of developmental disorders that includes autism, and Asperger syndrome. "Using genome-wide association studies, VWA8 has been associated with autism spectrum disorders (ASDs)." (PMID 34660594, 2021).
cardiac hypertrophy (1 paper, 2021). "Zebrafish vwa8 morphants revealed several phenotypes such as developmental delay, cardiovascular anomalies (cardiac edema and cardiac hypertrophy), disorganized notochord, severe skeletal anomalies, lack of locomotion, and scoliosis." (PMID 34660594, 2021). "The zebrafish vwa8-i1e2 morphants also exhibited heart defects and showed cardiac oedema and cardiac hypertrophy (C1)." (PMID 34660594, 2021).
COVID-19 (1 paper, 2022). A disease caused by infection with severe acute respiratory syndrome coronavirus 2. "Only one gene, VWA8 (Von Willebrand factor A domain-containing protein 8), was shared in the list of COVID-19 associated loci and in our MIS-C associated DNA methylation sites." (PMID 35770252, 2022).
familial hemiplegic migraine (1 paper, 2021). A migraine disorder characterized by individual and family history of aura that includes motor weakness. "VWA8 (KIAA0564) also showed putative ATPase activity expressed in the brain, as seen in patients with familial hemiplegic migraine (FHM II), where ATP1A2 is mutated, which encodes for two subunits of Na+/K+ ATPases, expressed in the adult brain." (PMID 34660594, 2021).
cancer (2 papers, 2023 to 2025). A tumor composed of atypical neoplastic, often pleomorphic cells that invade other tissues. "The outstanding associations between C-to-U RESs across different cancer types and different ICCs were also impressive, for example, CAVIN1 RESs with CD4+ T cells or M2 macrophages, and VWA8 with M1 or M2 macrophages." (PMID 36969056, 2023). "We also identified the top 1 GEAR in individual cancer types, such as TLL1 (BLCA), PGK1 (BRCA), RFXANK (CESC), DPP7 (COAD), VWA8 (KIRC), SCMH1 (LGG), HILPDA (LIHC), TLE1 (LUAD), CD151 (LUSC), ANKRD13A (OV), SOCS2 (PAAD), DRG2 (PRAD), ADAMTS6 (STAD), PSMB8 (THCA), ASS1 (UCEC)." (PMID 41404730, 2025).
adenocarcinoma (1 paper, 2016). A common cancer characterized by the presence of malignant glandular cells. "We however also observed one protein that was down-regulated in SCC while up-regulated in adenocarcinoma (VWA8) and vice versa 7 proteins showing the opposite behavior (FAK2, PMM2, K2C5, SMCA5, FAD1, DTX3L and CLU)." (PMID 26930711, 2016).
tumor (1 paper, 2022). "Conversely, proteins of interest in tumor-bearing rats elevated following OKN-007 treatment included ABCA6, ADAMTS18, VWA8, MACF1, and LAMA5." (PMID 35053843, 2022). "Conversely, proteins of interest in tumor-bearing rats that were elevated following OKN-007 treatment included ABCA6, ADAMTS18, VWA8, MACF1, and LAMA5." (PMID 35053843, 2022).
VWA8 also shares sentences with these, for which no sentence is quoted: schizophrenia (2 papers); Airway obstruction (1); cognitive disorder (1); coronary artery disease (1); developmental delay (1); emphysema (1); migraine (1); neurological disorders (1); psychiatric disorder (1); scoliosis (1).